SUGT1 (SGT1 assembly cochaperone of MIS12 kinetochore complex)
Description:
May play a role in ubiquitination and subsequent proteasomal degradation of target proteins.
Synonyms: SGT1
Tractability: PROTAC: UniProt records ubiquitination sites on it; ubiquitination databases record sites on it; its protein half-life has been measured.
Gene: Protein-coding gene on chromosome 13 (52,652,682 to 52,700,909, forward strand). Ensembl gene ENSG00000165416.
Subcellular location: Cytoplasm; Nucleus
Subcellular location (Human Protein Atlas): Cytosol; Nuclear bodies; Acrosome; End piece; Flagellar centriole; Mid piece; Principal piece
Pathways (Reactome):
Disease: Purinergic signaling in leishmaniasis infection
Immune System: The NLRP3 inflammasome
Gene Ontology:
Molecular function: protein binding; lncRNA binding; protein-folding chaperone binding
Biological process: kinetochore assembly; regulation of protein stability
Cellular component: cytosol; nuclear body; protein-containing complex; kinetochore; ubiquitin ligase complex; cytoplasm; nucleus
Genetic constraint (gnomAD): Loss-of-function variants: 8 observed, 41.6 expected, observed/expected ratio (o/e) 0.19, 90% interval 0.11 to 0.35. The upper end of that interval is the gene's LOEUF score, 0.35, which puts it in group 1 of 6, group 1 being the genes least tolerant of losing a copy. Missense variants: 277 observed, 319.71 expected, observed/expected ratio (o/e) 0.87, 90% interval 0.79 to 0.96. Synonymous variants: 106 observed, 111.79 expected, observed/expected ratio (o/e) 0.95, 90% interval 0.81 to 1.11.
Homologues: Orthologues: chimpanzee SUGT1 (99% identical), pig SUGT1 (93% identical), macaque SUGT1 (92% identical), dog SUGT1 (92% identical), mouse Sugt1 (88% identical), rat Sugt1 (82% identical), guinea pig SUGT1 (70% identical), tropical clawed frog sugt1 (64% identical), zebrafish sugt1 (59% identical), Caenorhabditis elegans unc-45 (13% identical), Drosophila melanogaster unc-45 (12% identical). Paralogues in human: RPAP3 (19% identical), SPAG1 (19% identical), UNC45B (18% identical), UNC45A (16% identical), SPATA16 (15% identical), SGTA (14% identical), STIP1 (13% identical), ST13 (13% identical), SGTB (13% identical), TTC12 (12% identical), TTC31 (12% identical), TOMM34 (12% identical), and 6 more.
Diseases named in the same sentence as SUGT1 in open-access papers:
SUGT1 is named in the same sentence as 14 diseases in open-access papers, as found by Europe PMC text mining. Sharing a sentence is not in itself a finding about the gene and the disease. The quoted sentences say what the papers report.
Alzheimer disease (2 papers, 2013 to 2015). A progressive, neurodegenerative disease characterized by loss of function and death of nerve cells in several areas of the brain leading to loss of cognitive function such as memory and language. "The Sugt1 protein is abundant in the brain, and cortical neurons expressing Sugt1 are decreased in Alzheimer's disease patients compared to healthy controls." (PMID 23738220, 2013).
colorectal cancer (2 papers, 2022 to 2023). A primary or metastatic malignant neoplasm that affects the colon or rectum. "High expression of SUGT1 is linked with human colorectal cancer." (PMID 36412907, 2022).
adenoma (1 paper, 2020). A neoplasm arising from the epithelium. "Of notice, the RT-PCR with junction specific primers of MRPS31 and SUGT1 genes was confirmed in both the adenomas and cancer tissues of three patients." (PMID 32992457, 2020).
asthma (1 paper, 2020). "SUGT1 variants have been significantly GWAS-associated with respiratory diseases with a strong inflammatory component, such as asthma." (PMID 32614437, 2020). "Moreover, variants in SUGT1 have been GWAS-associated with asthma (P = 7×10−12) and respiratory system disease (P = 2×10−14)." (PMID 32614437, 2020).
gastric cancer (1 paper, 2022). A primary or metastatic malignant neoplasm involving the stomach. "The ability of SUGT1 to inhibit the proliferation of gastric cancer cells by regulating AKT phosphorylation makes it a potential therapeutic target for gastric cancer." (PMID 35601407, 2022).
HIV-1 infection (1 paper, 2021). The type species of lentivirus and the etiologic agent of acquired immunodeficiency syndrome (AIDS). "SUGT1 regulates HIV-1 infection by stabilizing the positive end of microtubules." (PMID 34699307, 2021).
Paget disease (1 paper, 2024). A malignant neoplasm composed of large cells with large nuclei, prominent nucleoli, and abundant pale cytoplasm (Paget cells). "For example, LPP is implicated in paget disease, DNAJC16 plays a crucial role in coordinating immune responses, and SUGT1 provides resilience against Haemonchus contortus." (PMID 38684985, 2024).
sarcopenia (1 paper, 2023). Progressive decline in muscle mass due to aging which results in decreased functional capacity of muscles. "Moreover, Sugt1 loss leads to premature aging of the mice with aggravated sarcopenia progression." (PMID 39872547, 2023). "Altogether, our findings uncover the functional and mechanistic role of Sugt1 in MuSCs during regeneration and aging, indicating that Sugt1 can be a potential therapeutic target for sarcopenia treatment." (PMID 39872547, 2023).
cancer (5 papers, 2016 to 2024). A tumor composed of atypical neoplastic, often pleomorphic cells that invade other tissues. "The overexpression of Sugt1, a cochaperone of Hsp90, has been found in many cancer types including LSCC and contributes to the development of these cancers." (PMID 27517633, 2016). "Notably, Sanger sequencing and BLAST analyses among the amplicons produced from cDNA of polyps and carcinomas and MRPS31P5 showed higher sequence identity (100% similarity) than the fusion MRPS31-SUGT1 (90% similarity with exon 6 of MRPS31 and 98% similarity with exon 3 of SUGT1)." (PMID 32992457, 2020).
tumor (2 papers, 2020 to 2023). "To test the functional link between Sugt1 and Trim21, we realized that Trim21 has been reported to catalyze p21 ubiquitination and degradation with its E3 ubiquitin ligase activity and Trim21 deficiency is highly related to tumor cell proliferation and cellular senescence." (PMID 39872547, 2023).
SUGT1 also shares sentences with these, for which no sentence is quoted: Autoimmunity (1 paper); bladder cancer (1); colon cancer (1); respiratory system disease (1).